PTX3 (pentraxin 3)
Diseases named in the same sentence as PTX3 in open-access papers (continued):
Sharing a sentence is not in itself a finding about the gene and the disease.
fungal infections (16 papers, 2009 to 2025). "Genome-wide association studies (GWAS) have identified variants in immune-related genes, such as PTX3, associated with impaired neutrophil function and increased susceptibility to fungal infections." (PMID 40565568, 2025). "This protective role of PTX3 is supported by studies involving PTX3-deficient mice, which showed higher susceptibility to fungal infections." (PMID 39594709, 2024). "Results in a large cohort of patients with fungal infections after solid organ transplantation and in 2,609 bone marrow transplanted patients and their donor pairs further reinforced the association of PTX3 gene SNPs and susceptibility to fungal infection." (PMID 29204145, 2017). "The novel biomarkerpanel (TafC-Rhf-Ptx3) demonstrated improved accuracy in detectinginvasive fungal infections, which is critical for timely and effectivemanagement." (PMID 40488006, 2025). "PTX3 plays a crucial role in immune defense, particularly innate immunity, against fungal infections in the lungs by enhancing macrophages phagocytosis, promoting complement deposition, and forming protein complexes to facilitate fungal clearance." (PMID 40313930, 2025). "Pentraxin 3 (Ptx3) is an acute-phase protein that specifically targets fungal galactosaminogalactan and has been proposed as a promising biomarker for invasive fungal infections." (PMID 40576635, 2025). "Previous studies in mice have shown that knockout of PTX3 is associated with increased susceptibility to fungal infections in non-neutropenic patients due to impaired conidial opsonization." (PMID 40565568, 2025). "However, the Ptx3 assay effectively distinguished invasive fungal infection (IPA/IPM) from fungal colonization and IPA from CPA." (PMID 36422015, 2022). "Our results show that COPD patients have higher Ptx3 levels than control cohorts but not to the degree that could cause the misdiagnosis of fungal infections, if our proposed cutoffs are utilized." (PMID 36422015, 2022). "Moreover, macrophages express higher levels of PTX-3 in the presence of zymosan and it has been suggested that during fungal infection, secreted PTX-3 may enhance clearance by opsonising the pathogen and facilitating its uptake by Dectin-1." (PMID 19261355, 2009). "Invasive fungal infections, including IPA, can be diagnosed in just a few hours by monitoring Ptx3 levels in BALF." (PMID 36422015, 2022). "Experimental and clinical evidence indicates that the long pentraxin PTX3 and the short pentraxin SAP are key players in the host resistance to fungal infections, particularly those mediated by A. fumigatus." (PMID 34868070, 2021). "Our research group’s fundamental goal is to develop a combined analysis that simultaneously targets non-specific protein host factors such as Ptx3 and highly specific metallophore fungal biomarkers to improve the early diagnosis of fungal infection." (PMID 36422015, 2022). "Importantly, PTX3 is stored in neutrophil granules and is found within NETs, highlighting a potential involvement of PTX3 SNPs in both NET formation and their effectiveness against fungal infection." (PMID 38651925, 2024).
pulmonary fibrosis (16 papers, 2012 to 2025). Chronic progressive interstitial lung disorder characterized by the replacement of the lung tissue by connective tissue, leading to progressive dyspnea, respiratory failure, or right heart failure. "Increased alveolar area and reduced lung fibrosis were observed in bleomycin‐induced systemic Ptx3‐deficient mice." (PMID 36336784, 2022). "Elevated PTX3 levels are also associated with ECM formation‐induced fibrocyte differentiation in pulmonary fibrosis lesions." (PMID 36336784, 2022). "Our results suggested that targeting PTX3 significantly recovered body weight loss, reduced the severity of pulmonary fibrosis, and decreased the extent of pulmonary damage in the therapeutic treatment model." (PMID 36336784, 2022). "Consistent with our results that mimicked therapy and anti‐inflammation with induction of Ptx3 loss and αPTX3i administration, the dose and timing of PTX3‐based therapy in lung fibrosis must be investigated in the future." (PMID 36336784, 2022). "The protective effect of PTX3 on lung fibrosis was confirmed in a second set of experiments performed on Ptx3−/− animals in which PTX3 deficiency caused an increased deposition of fibrotic tissue and a rapid animal death following BLM administration." (PMID 33679758, 2021). "In murine models of lung fibrosis, PTX3 is present in fibrotic areas, and the PTX3 distribution is associated with collagen deposition." (PMID 25774777, 2015). "The minor allele of rs2305619 has been found significantly associated with higher plasma PTX3 levels and with disease severity in lung-transplant patients with idiopathic pulmonary fibrosis." (PMID 23285251, 2012). "Moreover, there was a positive correlation between elevated PTX3 levels and the elevated risk of graft dysfunction in lung transplant recipients with idiopathic pulmonary fibrosis." (PMID 31354697, 2019). "To determine if PTX3 is associated with human lung fibrosis, we examined the distribution of PTX3 in lung tissue from chronic obstructive pulmonary disease (COPD) patients with relatively normal lungs (> 80% FVC) and idiopathic pulmonary fibrosis (IPF) patients (<50% FVC)." (PMID 25774777, 2015). "The role of ptx3 in tissue remodeling is mainly related to turnover of fibrin-rich deposits at wound sites, and like MMP-12, ptx3 is also considered to have a role in the development of pulmonary fibrosis." (PMID 38702427, 2024). "Microarray analysis performed on human lung samples collected from patients with idiopathic pulmonary fibrosis showed a substantial downregulation of the ptx3 expression." (PMID 38702427, 2024). "To examine the clinical relationship of PTX3 in pulmonary fibrosis, we further assessed PTX3 expression in patients with fILD and matched control subjects (without fILD)." (PMID 36336784, 2022). "Taken together, our study provides new insight into the regulation of PTX3 in pulmonary fibrosis and a potential target for developing a future novel therapy for fILDs." (PMID 36336784, 2022). "Significantly, the down-regulation of PTX3 expression has recently been demonstrated in patients with idiopathic pulmonary fibrosis." (PMID 36362273, 2022). "The results showed that PTX3 inhibition improved the outcome of lung fibrosis in bleomycin‐induced lung injury and fibrosis." (PMID 36336784, 2022). "Results reported by Maccarinelli and colleagues and our observations indicate a protective and regulatory role of PTX3 in BLM-induced lung fibrosis models of lung injury." (PMID 34276664, 2021). "In the present study, we investigated the impact of endogenous PTX3 in a BLM-induced murine model of lung fibrosis." (PMID 33679758, 2021). "BLM was administered intratracheal to Ptx3 null mice and lung fibrosis was followed in parallel to that occurring in WT and Tie2-PTX3 animals." (PMID 33679758, 2021). "In this study we investigated the expression of PTX3 in a BLM-induced murine model of lung fibrosis with the aim to define its role in this pathological context." (PMID 33679758, 2021).
pulmonary fibrosis (continued). "Overall, in this study we have reported the observational results of the effect of endogenous PTX3 modulation on lung fibrosis onset and phenotype." (PMID 33679758, 2021). "On the other hand, a study by Diamond and colleagues reported that patients with idiopathic pulmonary fibrosis and chronic obstructive pulmonary disease showed higher levels of PTX3 6 h and 24 h after reperfusion when compared with controls." (PMID 31354697, 2019). "In lung tissue from pulmonary fibrosis patients, PTX3 has a widespread distribution, both in unaffected tissue and in fibrotic lesions, whereas SAP is restricted to areas adjacent to vessels, and absent from fibrotic areas." (PMID 25774777, 2015). "In the lung tissue from pulmonary fibrosis patients, PTX3 was distributed throughout the tissue, including the lung epithelium, alveolar leukocytes, and fibrotic areas, but PTX3 distribution was reduced within fibroblastic foci." (PMID 25774777, 2015). "To determine if PTX3 was also upregulated in pulmonary fibrosis, we stained lung tissue from mice that aspirated bleomycin or saline." (PMID 25774777, 2015). "Pentraxin 3 (Ptx3) has been shown to protect against BLM‐induced lung fibrosis in mice as well." (PMID 38991987, 2024). "Our results of αPTX3i safety, therapeutic efficiency in pulmonary fibrosis and compared with pirfenidone and nintedanib support that targeting PTX3 may be an effective strategy for lung injury‐induced fibrosis." (PMID 36336784, 2022). "Our data show that pulmonary PTX3 expression is upregulated during lung fibrosis." (PMID 33679758, 2021). "In addition, by using both transgenic PTX3-overexpressing mice and Ptx3 null animals, we demonstrate that endogenous PTX3 exerts a protective effect in BLM-induced lung fibrosis." (PMID 33679758, 2021). "Pentraxin 3 (PTX3) is produced, under appropriate conditions, by monocyte-macrophages, and it has been recognized as a major promoter of fibrocyte differentiation, both in vitro and in murine models of pulmonary fibrosis." (PMID 30956776, 2019). "The role of PTX3 in lung injury‐associated progressive pulmonary fibrosis has not been elucidated." (PMID 36336784, 2022). "Notably, our findings indicated that PTX3 was associated with enhanced pulmonary fibrosis and myofibroblast activation, which suggests that PTX3 is involved in ECM production and collagen deposition and contributes to pulmonary fibrosis." (PMID 36336784, 2022). "Thus, in summary, we assessed the involvement of PTX3 in pulmonary fibrosis." (PMID 34276664, 2021). "Similarly, the collectin Pentraxin 3 can both be produced in lung endothelial cells in response to IL-1 or in lung fibroblasts in response to TNF-α and is associated with pulmonary fibrosis." (PMID 29100778, 2017). "Although recent studies demonstrated an association between macrophages derived PTX3 and tissue fibrosis in nonalcoholic fatty liver disease as well as in lung fibrosis, whether PTX3 causes fibrosis or not is still unclear." (PMID 27597803, 2016). "Herein, we provide new insights on the possible role of PTX3 in the development of IPF and BLM-induced lung fibrosis." (PMID 34276664, 2021). "In keeping with previous observations in preclinical models of lung fibrosis and in lung tissue from IPF patients, PTX3 expression rapidly increases in the lungs of BLM-treated animals both at mRNA and protein levels." (PMID 33679758, 2021). "BMP, body mass index, mucin-1, pentraxin 3; DLCO, diffusion capacity for carbon monoxide; fILD, fibrosing interstitial lung diseases; FVC, forced vital capacity; GAP, gender-age-physiology; Interm., intermediate; IPF, idiopathic pulmonary fibrosis." (PMID 41392102, 2025). "Plasma PTX2 levels were not changed in bleomycin‐exposed Ptx3‐deficient mice or αPTX3i‐treated mice, which suggests that PTX2 is not involved in PTX3‐regulated pulmonary fibrosis." (PMID 36336784, 2022).
pulmonary fibrosis (continued). "Based on the literature and recent data, we propose that PTX3 may have a physiological and protective role during IPF, interacting with various circuits and representing a potential therapeutic target, acting as a pro-resolutive molecule in the context of pulmonary fibrosis." (PMID 34276664, 2021).
acute kidney injury (15 papers, 2011 to 2025). Sudden and sustained deterioration of the kidney function characterized by decreased glomerular filtration rate, increased serum creatinine or oliguria. "Another study showed that PTX3 treatment inhibited interstitial fibrosis induced by an acute kidney injury, reduced serum creatinine levels, and decreased the expression of collagen and smooth muscle actin in mice." (PMID 29725602, 2018). "The aim of this study was to develop an in vitro experimental model of acute kidney injury and to analyze the protective mechanism of exogenous recombinant PTX3." (PMID 29672566, 2018). "Serum PTX3 levels were significantly higher in patients with hematuria (P = 0.014), leucocyturia (P = 0.002), acute renal failure (P = 0.001), and nephrotic syndrome (P = 0.036)." (PMID 26817892, 2016). "Increased levels of PTX3 have been seen in ischemia-reperfusion injury as well as patients with septic shock and acute kidney injury." (PMID 26062689, 2015). "A study indicated a correlation between septic shock and acute kidney injury (AKI), revealing that the genes PTX3, VMP1, OLFM4, SLPI, TIMP1, LCN2, and S100A9 are strongly correlated with novel biomarkers implicated in the onset and progression of sepsis‐associated acute kidney injury (SSAKI)." (PMID 41394771, 2025). "Sepsis may also induce acute kidney injury (AKI), and studies showed that VMP1, SLPI, PTX3, TIMP1, OLFM4, LCN2, and S100A9 genes were markedly correlated with the development and progression of septic-shock-associated AKI." (PMID 36299685, 2022). "Patients within the highest tertile of PTX3 level had more often signs of AHF and acute kidney injury." (PMID 25922551, 2015). "Novel putative mediators of acute kidney injury (AKI) include immune-cell derived tumour necrosis factor-like weak inducer of apoptosis (TWEAK), angiopoietin-2 (Ang-2) and protein pentraxin-3 (PTX3)." (PMID 26519056, 2015). "In clinical data, serum PTX3 levels were significantly higher in patients with the following clinical manifestations, including noninfectious leucocyturia (P = 0.002), acute renal failure (P = 0.001), and nephrotic syndrome (P = 0.036)." (PMID 26817892, 2016). "We found that the differences of some indices, including leukocyturia (noninfection), acute renal failure, nephrotic syndrome, urine protein, and serum creatinine value, were more significant in PTX3 group than the other 2 groups." (PMID 26817892, 2016). "For example, a lack of PTX3 aggravated post-ischemic acute kidney injury, followed by tubular atrophy, interstitial fibrosis, and kidney shrinkage, while injection of recombinant PTX3 up to 6 h after reperfusion prevented renal leukocyte recruitment and post-ischemic kidney injury." (PMID 29492210, 2018). "The study shows that PTX3 may be used to predict all variables indicative of severe disease, i.e. hypotension, mechanical ventilation, low platelet count, high SOFA score, need of ICU treatment and renal failure." (PMID 21423699, 2011).
aspergillosis (15 papers, 2018 to 2026). Aspergillosis is an infection, growth, or allergic response caused by the Aspergillus fungus. "Despite genetic replication studies are in general scarce, the link between genetic polymorphisms in PTX3 (rs1840680) and rs7309123 (CLEC7a) and aspergillosis risk have been successfully replicated." (PMID 36733397, 2022). "Polymorphisms in Toll-like receptors such as TLR4, C-type lectin receptors such as dectin-1, and other pattern recognition receptors such as Pentraxin 3 (PTX3) have been found to be associated with susceptibility to aspergillosis." (PMID 35407478, 2022). "Our previous research found that COPD patients with pulmonary aspergillosis have a high prevalence of PTX3 polymorphisms." (PMID 34915889, 2021). "A recent report described a link between PTX3 polymorphisms and susceptibility to aspergillosis in patients undergoing hematopoietic stem-cell transplantation and lung transplant recipient." (PMID 34915889, 2021). "One study has also shown a significant association between PTX3 SNPs and the susceptibility to pulmonary aspergillosis in patients with Chronic Obstructive Pulmonary Disease (COPD)." (PMID 31031772, 2019). "Recently, polymorphisms in the human PTX3 gene have also been associated with aspergillosis in patients undergoing hematopoietic stem cell transplantation." (PMID 29801518, 2018). "Administration of PTX3 restores antifungal host responses in humans and mice, but more studies are needed to understand the precise mechanism underlying how PTX3 coordinates the host response against aspergillosis in humans." (PMID 29801518, 2018). "PTX3 polymorphisms have already been shown to greatly influence the susceptibility of patients to aspergillosis, probably due to mRNA instability in some SNPs." (PMID 30319631, 2018). "The BALF samples from 22 patients with proven or probable aspergillosis were assayed for human pentraxin 3 (Ptx3), fungal ferricrocin (Fc), and triacetylfusarinine C (TafC) in a retrospective study." (PMID 36422015, 2022). "The detection of Aspergillus siderophores and elevated Ptx3 can discriminate aspergillosis from mucormycosis." (PMID 36422015, 2022). "The median plasma PTX3 level of aspergillosis patients was 6.97 ng/mL, which is higher than the median plasma PTX3 level of 3.74 ng/mL found in IPA patients in the present study." (PMID 34915889, 2021). "In the M90T-infected wild type mice, the serum level of PTX3 was between 10 to 20 ng/mL after 72 h of infection, which was in the range of that observed in the plasma of shigellosis patients and in patients of aspergillosis." (PMID 30532257, 2018). "Another target could be Pentraxin 3 (PTX3), which has been shown to be a promising marker for aspergillosis." (PMID 35794908, 2022). "For instance, PTX3 encoding pentraxin 3 has been reported to increase susceptibility to A. fumigatus infection in a PTX3-/- mouse model and was elevated in BAL samples of IPA patients suffering from pulmonary aspergillosis." (PMID 35205926, 2022). "Patients with pulmonary aspergillosis, tuberculosis, dengue virus infection, meningococcal disease leptospirosis and shigellosis have increased PTX3 plasma levels that correlate with disease severity and could act as predictor of unfavorable outcomes." (PMID 31031772, 2019). "The essential role of PTX3 in host antifungal defense was established in vivo through the heightened susceptibility of mice lacking PTX3 to experimental aspergillosis and the observation that administration of exogenous PTX3 rescued antifungal effector functions and restored survival." (PMID 38651925, 2024). "Furthermore, identifying signature proteins may contribute to improving diagnosis of aspergillosis or provide new therapeutic leads as shown with PTX3 or SP-D." (PMID 34122441, 2021). "When PTX3 and GM were both positive in plasma or BALF, the specificity for the diagnosis of pulmonary aspergillosis was over 90%." (PMID 34915889, 2021).
aspergillosis (continued). "The median Ptx3 concentrations in patients with and without aspergillosis were 4545.5 and 242.0 pg/mL, respectively (95% CI, p < 0.05)." (PMID 36422015, 2022).